CRP (C-reactive protein)
Diseases named in the same sentence as CRP in open-access papers (continued):
Sharing a sentence is not in itself a finding about the gene and the disease.
diabetes (continued). "A similar analysis of data between groups showed that males with diabetes had higher (P < 0.05) levels of peroxides and CRP but lower WHR than their control counterpart." (PMID 27298824, 2016). "The meta-analysis demonstrated an overall relationship between CRP and diabetes, but there was a substantial heterogeneity in the results between studies, which reduced the degree of evidence in the meta-analysis." (PMID 27581604, 2016). "A community-based study performed in Scotland and England defined metabolic health status based on BP, high-density lipoprotein-cholesterol, diabetes, waist circumference, and C-reactive protein levels." (PMID 27445194, 2016). "Our current study expands on this research by investigating the effect of several cardiometabolic abnormalities, including CRP, on the relationship between depression and diabetes." (PMID 27227974, 2016). "FBG, 2hPG, HbA1C, FMD and hr-CRP in normotensive or prehypertensive women with diabetes mellitus were significantly higher than those in normotensive or prehypertensive women without diabetes mellitus (P < 0.05)." (PMID 26936372, 2016). "Inflammatory markers (C-reactive protein and fibrinogen) and lifestyle factors were measured repeatedly; diabetes incidence (new cases) was monitored over 7.5 years of follow-up." (PMID 27101929, 2016). "Age over 65 years, diabetes and CRP over 150 mg/l were identified as independent preoperative risk factors for conversion." (PMID 27891173, 2016). "Seo and colleagues reported a significant positive correlation between hs-CRP and various cardiovascular risk factors in Korean patients with CVD or diabetes mellitus." (PMID 27589783, 2016). "The aim of this prospective study is to investigate the relationship between plasma levels of five acute-phase proteins (CRP, ceruloplasmin, alpha-1-antitrypsin, orosomucoid, and haptoglobin) at baseline and incidence of diabetes in a population-based cohort." (PMID 27581604, 2016). "Epidemiological studies have demonstrated that increased levels of mediators of inflammation and acute-phase reactants, such as fibrinogen, C-reactive protein (CRP), and IL-6, correlate with the incidence of type 2 diabetes mellitus (T2DM)." (PMID 27070352, 2016). "The prevalence of cardiovascular risk factors across continents is heterogeneous; however, some regions with the highest hs-CRP levels also have the highest prevalence of hypertension, diabetes, and obesity." (PMID 27166776, 2016). "The present study revealed significant associations between the acute-phase proteins orosomucoid, haptoglobin, and CRP and increased incidence of diabetes when adjusted for several potential confounders." (PMID 27581604, 2016). "The other predictors were male sex (OR: 1.28, 95% CI: 1.13–3.4), diabetes mellitus (OR: 1.93, 95% CI: 1.1–11.2), and C-reactive protein (CRP, OR: 1.67, 95% CI: 1.21–6.41)." (PMID 27239372, 2016). "Apart from weight loss and adequate glycaemic control, improving BP, insulin resistance, and CRP and lipid profiles can also play an important role in lowering CVD risk in diabetes." (PMID 27187457, 2016). "Amongst subjects with normal CRP or ferritin, 9.8% had diabetes (known or newly detected during OGTT)." (PMID 26347777, 2015). "Lastly, the distribution of health conditions show 10% of respondents with HWC and HBP had intermediate CRP levels, whereas 15% of the population with diabetes were in this category." (PMID 26703686, 2015). "For example, patients with biliary tract infections and primary bacteremia had greater rates of diabetes mellitus, and liver cirrhosis, malignancy, and higher level of C-reactive protein than patients with acute gastroenteritis." (PMID 25602257, 2015). "After adjustment for clinical covariables (age, CRP, diabetes and a history of cardiovascular disease) both sTNFRs remained independently associated to outcomes (HR: sTNFR1: 1.51, 95% CI: 1.30-1.77; sTNFR2: 1.13, 95% CI: 1.06-1.20)." (PMID 25823004, 2015).
diabetes (continued). "Diabetes, hs-CRP-increased use of CCBs, and use of β-blockers were found to be independent risk factors for CR." (PMID 25452814, 2015). "Of subjects with high CRP or ferritin, 41% had either diabetes (all newly detected) or impaired glucose tolerance during OGTT (a higher proportion than those with normal CRP or ferritin, P < 0.001)." (PMID 26347777, 2015). "In particular, the Diabetes Control and Complications Trial, as well as a number of other studies, revealed that hs-CRP levels increased in patients undergoing intensive therapy." (PMID 26273677, 2015). "Biomarkers of obesity (leptin, adiponectin), diabetes (glucose, insulin), inflammation (C-reactive protein, Interleukin-6, surface tumor necrosis factor receptor (sTNFR) I & II) and oxidative stress (F2-isoprostanes) were measured in stored blood samples." (PMID 26380096, 2015). "CRP – an acute-phase protein – is commonly used marker, which participates in low-grade inflammation in diabetes." (PMID 26578953, 2015). "Associations have been inconsistent for coronary calcification score and serum intact PTH, C-reactive protein, serum calcium, serum creatinine, cholesterol, diabetes, smoking, and hypertension." (PMID 26269747, 2015). "Moreover, the diabetic and anemic patients had high levels of C-reactive protein and ferritin ultrasensible; however, these diabetic and anemic patients had low iron contents, showing that ferritin increases were associated with chronic inflammatory process present in diabetes." (PMID 26640706, 2015). "Local melatonin application in patients with diabetes and periodontal disease resulted in a significant decrease in CRP and IL-6 serum levels as well as an improvement in the gingival index and pocket depth." (PMID 26644840, 2015). "Overall, the patients in the TG/HDL-C quintiles had different percentages of diabetes, lipid profiles, hs-CRP level, and nutritional status." (PMID 25761189, 2015). "At baseline, the association between age and esRAGE remained significant after controlling for the confounding effect of CRP in the diabetes group (B = −0.009, R2 = 0.082 and p = 0.009) and in girls with diabetes (B = −0.012, R2 = 0.123 and p = 0.008)." (PMID 26408307, 2015). "Another interesting result of the current study is the fact that higher CRP levels were found in diabetic rats, though the values are considered as inflammatory reaction occurrence in diabetes mellitus." (PMID 25864817, 2015). "A total of 14,228 participants who were free of diabetes (as ascertained from self-report or medical records), had data on CRP at baseline, and at least one measurement of HbA1c, were included in the present analysis." (PMID 25994228, 2015). "Other significant correlates of GGT and coronary plaques were smoking, diabetes, hypertension, hyperlipidemia, creatine, triglycerides, uric acid, HbA1c, and hs-CRP." (PMID 26543300, 2015). "Key words:Melatonin, periodontal disease, diabetes mellitus, interleukin-6, tumor necrosis factor-alpha, C-reactive protein, inflammatory markers." (PMID 26644840, 2015). "Conversely, male proportion, heart rate, SBP, DBP, BMI, FBG, TC, high-sensitivity CRP, uric acid, hypertension, diabetes, history of cardiovascular diease and lower income were negatively associated with a better health category of CVH score (P<0.05)." (PMID 26154254, 2015). "In multiple regression analyses we found significant associations between soluble variants of RAGE and the surrogate markers of atherosclerosis cIMT and CRP in the diabetes group." (PMID 26408307, 2015). "The BMI/WHtR 5-category variable was a significantly better discriminator of high triglycerides, low HDL-C, pre-diabetes, high C3, CRP, IL-6, TNF-α and WBC levels compared to BMI, and of leptin compared to WHtR." (PMID 26351521, 2015). "Patients who reached the composite endpoint, were older, had a higher CRP, lower albumin and had more often a history of cardiovascular disease or diabetes." (PMID 25823004, 2015).
diabetes (continued). "PAD in this study was independently associated with smoking, female gender, black race, hypertension, increasing age, C-reactive protein, diabetes duration, and lower BMI." (PMID 25133533, 2014). "Elevated levels of the inflammatory marker high-sensitivity C-reactive protein (hs-CRP) are associated with increased risk for CVD and diabetes mellitus." (PMID 25324698, 2014). "Diabetes is an inflammatory state, characterised by increased plasma levels of reactive oxygen species, lipid per oxidation products, CRP, ferritin and other reactive compounds, which all increase with inflammatory process." (PMID 25506584, 2014). "Additional adjustment for lifetime smoking, diabetes, hypertension, current CRP, current BMI, and age at first overweight (Model 4) attenuated the results further." (PMID 24482683, 2014). "Overall, the lowest female:male ratios observed were in rural/regional and remote settings.Using data available from included studies, mean HDL-C values were negatively associated with prevalence of diabetes, mean WHR and mean/median plasma levels of CRP." (PMID 24888391, 2014). "Elevated CRP levels are observed during infection, cardiovascular diseases, diabetes and malignancies." (PMID 25013512, 2014). "Eighteen per cent of respondents with higher levels of CRP and 13% of those with higher fibrinogen levels were classified as having diabetes." (PMID 24884735, 2014). "CRP-mf-4 was significantly associated with increased BMI, but not with other parameters of the metabolic syndrome (HDL-C and triglyceride levels, and diabetes)." (PMID 25299074, 2014). "Simple linear regression analysis showed that age, BMI, SBP, DBP, MAP, PP, BP classification, diabetes, hypertension, metabolic syndrome, TG, TC, LDL-C, HbA1c, and hs-CRP were significantly associated with D(f) (all, P≤0.010)." (PMID 25188273, 2014). "Independent predictors of incident CAD, determined by logistic regression, were as follows: cystatin C, hs‐CRP, eGFR, HDLc after adjustments for age, creatinine, eGFR, homocysteine, gender, presence of hypertension, and diabetes." (PMID 24478035, 2014). "For the crude ORs, the variables of age, diabetes duration, current smoking, SBP, hs-CRP, uric acid, ACR, and YZ score were linked with PAD." (PMID 24669230, 2014). "In animal models of diabetes, pumpkin seeds supplementation decreased serum glucose, triglyceride and cholesterol, and CRP levels." (PMID 24578648, 2014). "We cannot predict ischemic heart disease in a patient with diabetes using high sensitive C-reactive protein level, HbA1c level, UA findings, or LDL-C level." (PMID 24713330, 2014). "Thigh muscle appeared to be protectively and independently associated with diabetes, HbA1c, and CHD in South Asians, and CRP in Europeans." (PMID 24862429, 2014). "Diabetes, hypertension, atrial fibrillation, general atherosclerosis and CRP > normal level occurred much more often in the study group than in controls." (PMID 25145866, 2014). "The level of FPG (P<0.05), 2hPG (P<0.05), HbA1c (P<0.05) and C-reactive protein (P<0.05) was highest in those with concomitance of albuminuria and retinopathy, a subgroups with highest frequency of diabetes and metabolic syndrome." (PMID 24835219, 2014). "Multivariate logistic regression revealed significant correlations between PAD and, respectively, YZ score, age, diabetes duration, current smoking, and hs-CRP." (PMID 24669230, 2014). "For all the variables, BMI, smoking, diabetic mellitus, usage of statins, and plasma levels of Hs-CRP and APN significantly correlated with Hs-CRP/APN ratio (all p values < 0.05)." (PMID 25070472, 2014). "Both of albuminuria and high CRP are considered as strong and independent risk factors for CVD in patients with hypertension and diabetes as well as in the general population." (PMID 24835219, 2014).
diabetes (continued). "Independent associations of albuminuria were: males (OR 3.06 (95% CI, 2.23–4.19)), diabetes (OR 2.14 (1.53–3.00)), lower estimated glomerular filtration rate ((OR 2.06 (1.48–2.85) 30–44 vs 45–59), and high sensitivity CRP ((OR 1.70 (1.25–2.32))." (PMID 24867154, 2014). "In the present study, after adjusting for CRP as a marker of inflammation and/or oxidative stress, GGT was found to be a significantly associated with the incidence of diabetes in both sexes." (PMID 24502834, 2014). "Chronic inflammation indicated by an elevated C-reactive protein or interleukin-6 plays a critical role in the development of diabetes." (PMID 24504072, 2014). "Insulin resistance is known to be induced by inflammation arising from adipose tissue and elevated levels of CRP and IL-6 are shown to predict the development of diabetes." (PMID 25337037, 2014). "ABCA1 expression is reduced in patients with obesity-related metabolic diseases such as hypertension and T2DM, mouse models of insulin resistance and diabetes, and by pro-inflammatory mediators such as TNFα and CRP." (PMID 25045936, 2014). "In the US population, apolipoprotein measurements significantly predict CHD death, independently of conventional lipids and other CV risk factors (smoking, dyslipidaemia, hypertension, obesity, diabetes and C-reactive protein)." (PMID 25587314, 2014). "The association between ALP and CVD deaths is weakened but still exists after full adjustment, which implies that higher levels of ALP play such roles other than adjustment factors, such as GFR, diabetes mellitus, CRP and hepatic dysfunction." (PMID 25033287, 2014). "CRP, an acute phase reactant has been developed as a surrogate marker of inflammatory mediators in coronary artery disease and diabetes." (PMID 24502618, 2014). "BMI was positively associated with common obesity related characteristics such as higher blood pressure, diabetes, an unfavourable lipid profile, higher eGFR and CRP." (PMID 24885137, 2014). "Unlike that of leptin and LAR, serum hs-CRP levels were higher in non-obese Type 2 DM than that in obese subject, which is concordant with several cross-sectional studies showing an increase of CRP levels in patients with diabetes." (PMID 25276234, 2014). "Thigh muscle area largely retained inverse associations with diabetes, HbA1c, clinical and subclinical CHD and CRP, an effect greater for South Asians than Europeans for metabolic traits." (PMID 24862429, 2014). "Urine excretion of orosomucoid was increased in the patients with diabetes and normoalbuminuria and it correlated with markers of inflammation such as CRP and markers for endothelial dysfunction." (PMID 24143207, 2013). "FGF-23 was inversely associated with EF after multivariate adjustment for age, race, gender, diabetes, eGFR, serum C-reactive protein concentrations, LVH, and the use of β-blockers and ACE inhibitors (β –2.03; p = 0.004)." (PMID 23849306, 2013). "The concentration of cystatin C is influenced by high-dose glucocorticoid therapy, thyroid function and, to a lesser degree, C-reactive protein (CRP), diabetes mellitus, systolic blood pressure, age, smoking, gender and serum concentrations of other analytes." (PMID 23991042, 2013). "In summary, the levels of leptin, adiponectin, oxLDL, CRP, and triglycerides in patients with T2DM seem to be more associated with obesity and less with diabetes." (PMID 24634792, 2013). "In model 2, in which albumin was excluded, D/Pcr, peritoneal Kt/V urea, and pulse pressure remained in the model with the additional inclusion of diabetes and increased serum CRP levels (Model 2)." (PMID 23418538, 2013). "C-reactive protein can be used as a marker of acute inflammation and it also has been widely used for monitoring disease activity in cardiovascular disease and diabetes, which emphasizes the likely role of chronic inflammation in the aetiology." (PMID 23484158, 2013).
diabetes (continued). "Then, the area under the curve (AUCROC) was calculated for the parameters such as age, duration of diabetes, systolic and diastolic blood pressure, albuminuria, serum HbA1c, CRP, creatinine, and serum TGF-β1 levels." (PMID 23671881, 2013). "Inflammation affects insulin signalling and increases beta-cell death, and markers of inflammation, such as elevated interleukin 6 (IL-6) and C-reactive protein (CRP) levels, have been found to be associated with future diabetes risk." (PMID 23843750, 2013). "Multivariate analysis of women revealed that while the highest hs-CRP tertile was independently associated with CAS, diabetes mellitus and hypertension were negatively associated with CAS." (PMID 24204905, 2013). "Under pathological conditions, in addition to cancer, several comorbidities, including diabetes, cardiovascular disease, chronic hepatitis, smoking, and hypertension, have been reported to promote increases in serum CRP levels." (PMID 23724031, 2013). "By other word, among different predictors, only diabetes showed a significant relationship with higher serum CRP levels." (PMID 24523776, 2013). "This is comparable with other biochemical biomarkers used in the discrimination of HNF1A-MODY from other diabetes (e.g. hs-CRP (high sensitivity C-reactive protein) and 1,5Ag (serum 1,5 anhydroglucitol)) which both have ROC AUC ∼0.8." (PMID 23799006, 2013). "The prevalence of hypertension, diabetes rate, blood lipid levels, hs-CRP levels and prevalence of a body temperature of >37.5°C were higher in the progressive and non-progressive groups than in the control group (P<0.05)." (PMID 23737893, 2013). "The comparison between poor outcome and good outcome in patients with BAD showed significant differences with respect to CRP (p = 0.006), and diabetes mellitus (p = 0.011)." (PMID 24039853, 2013). "Correlation analyses revealed that PrCl was positively correlated with diabetes, pulse pressure, C–reactive protein (CRP) level, dialysate/plasma creatinine ratio (D/P cr) at 4 h, and peritoneal Kt/V urea." (PMID 23418538, 2013). "Two studies (one in smokers, and the other in patients with diabetes), reported an association between GSTT1 and GSTM1 null mutations and lower levels of the inflammatory biomarker CRP, itself associated with poor survival." (PMID 24083102, 2013). "In this study, SBP, CRP, lower serum albumin, uric acid, GGT and diabetes were significantly associated with albuminuria in the Aboriginal population." (PMID 23947772, 2013). "In the context of primary diabetes prevention, we are unaware of trials that have investigated CRP reduction for the prevention of diabetes development." (PMID 24155956, 2013). "Among the traditional risk factors, BMI, diabetes, HDL and total cholesterol were different across CRP categories, and BMI and WC were different across the BNP categories." (PMID 24244755, 2013). "The mean high sensitive C-reactive protein level was markedly higher in women than men in the normal and known diabetes groups." (PMID 23407904, 2013). "Patients with higher phosphorus levels were more likely to be older and females, and had higher prevalence of hypertension and diabetes, and had reduced renal function and hemoglobin and higher C-reactive protein levels." (PMID 23505492, 2013). "Multiple logistic regression showed that the numbers of cEPCs (OR 3.31, 95%CI 1.26-8.87, p = 0.025; IAS vs. CP) were an independent IAS marker after adjustment for hypertension, diabetes, smoking and CRP levels." (PMID 24188156, 2013). "The patients with T1DM and confirmed NPDR had a longer duration of diabetes, higher serum HbA1c levels, higher CRP, higher urinary albumin excretion, and systolic blood pressure values compared to the T1DM patients without retinopathy (P < 0.05)." (PMID 23671881, 2013). "Gender-specific stratified analysis for CAS of hs-CRP tertiles, and diabetes mellitus or hypertension." (PMID 24204905, 2013).